EGFR (epidermal growth factor receptor)
Diseases named in the same sentence as EGFR in open-access papers (continued):
Sharing a sentence is not in itself a finding about the gene and the disease.
squamous cell carcinoma (continued). "Third, the proportion of histopathological subtypes of NSCLC (adenocarcinoma and squamous cell carcinoma) varied significantly, as EGFR mutations are difficult to detect in squamous cell carcinoma patients who smoke, while EGFR mutations are more common in adenocarcinoma." (PMID 35515138, 2022). "Compared to A549 cells treated with serum-derived exosomes from ADK WT, squamous cell carcinoma, and healthy donors, A549 cells treated with exosomes from patients with an EGFR mutation showed a significant increase of vimentin and a slight decrease of E-cadherin, canonical markers of EMT." (PMID 35954442, 2022). "These include, among others, the identification of a subset of sinonasal carcinomas associated with HPV infection, the identification of a subset of squamous cell carcinomas with EGFR alterations, and of rare variants with chromosomal translocations (DEK::AFF2, ETV6::NTRK and others)." (PMID 35326613, 2022). "Regarding the histological type of the 12 patients with unknown EGFR mutations in our study, 10 were squamous cell carcinomas and 2 were large cell neuroendocrine carcinomas." (PMID 34696229, 2021). "Furthermore, the patients with adenocarcinoma having EGFR mutations were 28.2% (169/431), whereas only 5.4% of the patients with squamous cell carcinoma carried EGFR mutations." (PMID 33255238, 2020). "HPV infection was previously reported to cause EGFR overexpression in squamous cell carcinoma." (PMID 32850421, 2020). "However, the median progression-free survival in squamous cell carcinoma patients treated with EGFR tyrosine kinase inhibitors is worse than that in adenocarcinoma patients with EGFR mutations." (PMID 29849818, 2018). "The prognostic role of EGFR mutations in squamous cell carcinoma had rarely been reported." (PMID 28079142, 2017). "In a few studies, the rate of EGFR mutation reported was very low in squamous cell carcinoma." (PMID 28832323, 2017). "Therefore, some physicians proposed that re-administration of 1stor 2nd generation EGFR TKI to conquer acquire resistance in patients with lung non-squamous cell carcinoma initially harboring EGFR mutation." (PMID 28486985, 2017). "As EGFR signal activation is reported to be closely associated with chemoresistance or poor prognosis in squamous cell carcinomas as well as other malignancies, effective suppression of EGFR signaling is considered to be important for the treatment of these cancers." (PMID 28764725, 2017). "In squamous cell carcinoma, the EGFR mutation rate is reported to be approximately 5%." (PMID 27623437, 2016). "Notably, in this study we had one case of squamous cell carcinoma that harbors EGFR exon 19 mutation in the primary tumor, but the mutation was undetectable in metastases." (PMID 24398248, 2014). "Our findings suggest that EGFR mutation testing should be considered even for squamous cell carcinoma patients in East Asian populations, although further studies need to better characterize the prevalence of EGFR mutation testing in East Asian patients with squamous cell lung carcinoma." (PMID 23468851, 2013). "Our results showed that the overall frequency of TKIs sensitive EGFR mutations was 33.7%, and the EGFR mutation rate in squamous-cell carcinoma (14.5%), adenocarcinoma (52.9%) and adenosquamous carcinoma (39.5%) was higher than the data from previous Asian population-based studies." (PMID 24351833, 2013). "Because identical EGFR mutations have been seen in both the adenocarcinoma component and squamous cell carcinoma component in resected cases of adenosquamous carcinoma, it has been suggested that the two components may arise from a single clone." (PMID 23879483, 2013).
squamous cell carcinoma (continued). "In 1995, we reported that the human epidermoid carcinoma cells, A431, contain a small fraction of Src and EGFR in which these two kinase were in physical association with each other, and that Src phosphorylates EGFR on tyrosine 845 (Y845) in the Src-EGFR complex." (PMID 23702846, 2013). "The prevalence of EGFR mutations were 7.5% (5 out of 67), one exon 19 deletion, one L858R (exon 21) mutation both in adenocarcinomas and three G719X mutations (exon 18) which were found in squamous cell carcinomas (SCC) and NSCLC NOS." (PMID 26316935, 2012). "The aim of this study was to investigate the differences in EGFR overexpression, EGFR gene amplification, and activating mutations in the tyrosine kinase (TK) domain of this gene between squamous cell carcinomas and adenocarcinomas/adenosquamous carcinomas of the uterine cervix." (PMID 21730982, 2011). "In addition, EGFR-mutated squamous cell carcinoma patients had significantly worse DFS and OS compared to EGFR wild-type squamous cell carcinoma patients (15.0 versus 44.6 months, log-rank χ2 =3.839, P = 0.050 for DFS; 30.1 versus 52.9 months, log-rank χ2 = 7.870, P = 0.005 for OS)." (PMID 27072585, 2016). "Finally, while the prevalence of EGFR mutation positivity was 39% among adenocarcinoma patients, we found a that 11% of patients with squamous cell carcinoma also tested positive, suggesting that testing should be generalized to all NSCLC patients in East Asia." (PMID 23468851, 2013). "The different environmental and genetic backgrounds of tumours may also explain expression variation; squamous cell carcinoma is highly associated with smoking history and male gender, whereas adenocarcinomas frequently show EGFR mutations and occur more often in women." (PMID 21285982, 2011). "For instance, TP63 and SOX2 bind to the SEs and promoter of CCAT1, driving its expression and thereby activating the oncogenic EGFR pathway in squamous cell carcinoma." (PMID 39964764, 2025). "EGFR promotes migration of squamous cell carcinoma cells by activating the VAV2-Rac1 signaling pathway in endosomes." (PMID 39744818, 2025). "Histological analysis revealed that 38 patients (95%) had squamous cell carcinoma, whereas the remaining two with non-squamous cell carcinoma were confirmed as EGFR-positive." (PMID 40867300, 2025). "The majority of squamous cell carcinomas arising in the upper airway show EGFR overexpression; therefore, cetuximab is indicated for the treatment of this tumor type." (PMID 40149887, 2025). "The combination of the VEGF inhibitor bevacizumab with the EGFR inhibitor erlotinib in recurrent/metastatic squamous cell carcinoma of the head and neck is under phase 1 and 2 clinical trials." (PMID 40282457, 2025). "Cetuximab attachment resulted in a nanosystem capable of specific delivery of drugs to epidermal growth factor receptor (EGFR)-hyperexpressing cancer cells in epidermoid carcinoma." (PMID 41155904, 2025). "EGFR, the best known pro-oncogenic receptor, is overexpressed in squamous cell carcinoma A431 cells." (PMID 40264586, 2025). "Approximately 47 patients with EGFR-Mutant aNSCLC were recruited, including 1 squamous cell carcinoma (SCC) patient, 1 EGFR G719C mutated patient, 1 EGFR S768 patient mutated, and 1 EGFR KDD mutated patient." (PMID 40918464, 2025). "Our study was the first to investigate the co-expression of B7H3 and EGFR in NSCLC, with positive rates exceeding 50% across squamous carcinoma, adenocarcinoma, and EGFR-mutant subtypes." (PMID 41291854, 2025). "A431 was an epidermoid carcinoma cell line representing normal skin with significant EGFR overexpression and relatively low expression of B7H3." (PMID 41291854, 2025).
squamous cell carcinoma (continued). "It has been discovered that luteolin inhibits EGFR autophosphorylation and causes EGFR degradation through the lysosomal pathway in NSCLC and epidermoid carcinoma (A431) cells, respectively." (PMID 40728967, 2025). "Activation of EGFR in squamous cell carcinoma keratinocytes has been shown by EPA and DHA, along with 15-HETE in rat vascular smooth muscle cells." (PMID 39843435, 2025). "GST and GST tagged KDELR C tail were purified from E. coli, immobilized onto glutathione beads, and incubated with cell lysates prepared from a epidermoid carcinoma cell line, A431, which has a high endogenous level of EGFR." (PMID 38378560, 2024). "7MeERT also had higher antiproliferative activities in epidermoid carcinoma A431 cells overexpressing EGFR (IC50 = 5 μM) and cervical cancer HeLa cells (IC50 = 1 μM) compared to Ertredin (IC50 = 50 μM)." (PMID 39334963, 2024). "In our study, PD-L1 expression was significantly higher in squamous cell carcinomas and lower in adenocarcinomas, and was positively associated with MET and KRAS mutations, as well as the wild-type EGFR gene state." (PMID 38394518, 2024). "In contrast, luteolin has the highest binding affinity to EGFR, inhibits EGFR autophosphorylation, and promotes EGFR degradation via the lysosomal pathway in epidermoid carcinoma (A431) and NSCLC cells." (PMID 39519572, 2024). "The epidermal growth factor receptor (EGFR) was overexpressed in squamous cell carcinoma HN cells, which internalize GE11-conjugated liposomes." (PMID 38256959, 2024). "In Poland, the diagnosis of EGFR gene mutations is performed in patients with non-squamous cell carcinoma and, until recently, only in patients with advanced NSCLC (due to the reimbursement regulations for EGFR tyrosine kinase inhibitors therapy)." (PMID 38397927, 2024). "TOCA-1 has previously been studied in EGFR-activated A431 epidermoid carcinoma cells, where it has EGFR-dependent roles in filopodia, endocytosis and cell motility." (PMID 38323924, 2024). "The E-cadherin-dependent activation of EGFR leads to an increase in expression of the anti-apoptotic protein Bcl-2 and promotes survival of cells in multicellular aggregates formed by squamous cell carcinoma cells." (PMID 39594667, 2024). "For example, EVs derived from human squamous cell carcinoma cells transport epidermal growth factor receptor (EGFR) to ECs and enhance their angiogenic potential." (PMID 38318528, 2024). "This Ru-NB derivative was tested towards A431 human epithelial cancer cells (epidermoid carcinoma), and confocal imaging showed co-localization of Ru-NB with epidermal growth factor receptor (EGFR)." (PMID 39201338, 2024). "One individual with metastatic, chemotherapy-refractory squamous cell carcinoma of the maxillary sinus was found to have an EGFR exon 20 insertion." (PMID 39590164, 2024). "The parameters analyzed included histopathological type (NSCLC: squamous cell carcinoma or adenocarcinoma; SCLC), molecular mutations (EGFR, ALK, PD-L1), parameters from the complete blood count, inflammatory parameters, and associated comorbidities." (PMID 39199673, 2024). "EGFR overexpression is also commonly observed in various types of human squamous cell carcinomas, such as cutaneous squamous cell carcinoma, head and neck squamous cell carcinoma, and oral squamous cell carcinoma." (PMID 38785565, 2024). "Other genetic alterations to be identified in CC include MAPK1, EGFR, HLA-B, EP300, FBXW7, NFE2L2, and ERBB2 in squamous cell carcinoma and ELF3 as well as CBFB somatic mutations in adenocarcinoma." (PMID 39062539, 2024). "In the study, the PEGylated EV (EV pi Ega1) with R2‐PEG micelles, which drastically increased EVs binding to EGFR‐overexpressing cells (A431 cells, epidermoid carcinoma cells) compared to cells that lack EGFR expression (NeuroA2 cells)." (PMID 39167024, 2024). "In the field of human medicine, anti-EGFR therapies are promising in the treatment of squamous cell carcinoma." (PMID 38248333, 2024).
squamous cell carcinoma (continued). "EGFR and KRAS are two of the most mutated genes in adenocarcinomas, while these genes rarely change in squamous cell carcinoma." (PMID 39201328, 2024). "It was not until the 1980s that the corresponding receptor, epidermal growth factor receptor (EGFR), was successfully cloned and found to be amplified in A431 epidermoid carcinoma cells." (PMID 38601214, 2024). "Corresponding statistical test was performed to compare the parameters and protein expression between squamous cell carcinoma (SCC) and adenocarcinoma (AC), as well as EGFR mutations and wild-type." (PMID 38396128, 2024). "In order to confirm the most important hallmarks of our findings in patients, we next analyzed biopsies of EGFR-inhibitor-treated squamous cell carcinoma (SCC) cancer patients." (PMID 39521937, 2024). "Binding of the IRDye800CW-Fab2 and the Fab2 were characterized using flow cytometry with A-431 cells, an EGFR positive human epidermoid carcinoma cell line." (PMID 37419997, 2023). "Among the 37 squamous cell carcinoma NSCLC patients, 19 patients underwent genetic testing and 1 patient (2.7%) harboured EGFR exon 19 deletion mutation and 1 (2.7%) patient harboured KRAS-L19F mutation." (PMID 37208639, 2023). "Pharmacological inhibition or genetic suppression of mPGES1 inhibits EGFR phosphorylation both in human epidermoid carcinoma cells and in in vivo animal models of cancer, with a consequent reduction in tumor growth and inhibition of angiogenesis." (PMID 37190301, 2023). "In this patent, the authors reported that 100 μM menadione is the strongest EGFR activator, 1000 μM PK generates 1/10th of the effect of menadione, and MK-4 is ineffectual against human squamous cell carcinoma cells (A431)." (PMID 38092882, 2023). "In a cell-based assay, CD27xEGFR dose-dependently bound to the EGFR+ epidermoid carcinoma cell line A431." (PMID 37545491, 2023). "The recombinant and native lectins from Artocarpus integrifolia decrease the levels of EGFR phosphorylation in A431 epidermoid carcinoma cells." (PMID 37259433, 2023). "Preclinical studies indicate that inhibiting SMO can prompt the shift of basal cell carcinoma to squamous cell carcinoma by promoting c-FOS activation of the EGFR/RAS/MAPK pathway." (PMID 38067165, 2023). "In this study, 87.9% of EGFR-positive samples were squamous cell carcinomas and 6.1% each were adenocarcinomas and adenosquamous carcinomas." (PMID 38414930, 2023). "Because EGFR status and squamous cell carcinoma are highly colinear, we used Cox proportional regression with pathology type as a categorical variable for overall survival analysis." (PMID 36653333, 2023). "Lectins’ effect on EGFR has been studied in some human cancer cell lines, such as the epidermoid carcinoma A431 cells." (PMID 37259433, 2023). "The average percentage of squamous cell carcinoma overexpressing EGFR is 51% as compared with 38% for adenosquamous carcinomas and 23% for adenocarcinomas." (PMID 38414930, 2023). "We found previously that human peripheral blood and EGF can modulate the activities of EGFR-specific drugs on inhibiting clonogenity in model EGFR-positive A431 squamous carcinoma cells." (PMID 37626832, 2023). "Samples were collected from 20 cases with IP, 7 with IP and squamous cell carcinoma (IP-SCC), and 20 with SNSCC and examined for HPV infection and EGFR exon 20 mutations." (PMID 37109043, 2023). "Here, we demonstrate that human serum suppresses the impact of EGFR-targeted drugs cetuximab and erlotinib on the growth rate of A431 squamous carcinoma cells." (PMID 37626832, 2023). "EGFR has been found to stain more strongly in squamous cell carcinomas than adenocarcinomas and adenosquamous carcinomas." (PMID 38414930, 2023). "In this study, using human squamous carcinoma cell line A431, we showed a dramatic and donor-specific influence of human blood serum on the inhibition of cell growth rate by EGFR-targeted drugs." (PMID 37626832, 2023).
squamous cell carcinoma (continued). "Most patients whose samples were positive for EGFR were young, had squamous cell carcinoma and advanced diseases." (PMID 38414930, 2023). "The test rate (percentage tested of patients diagnosed with non-squamous cell carcinoma NSCLC) for EGFR has increased significantly (p < 0.001) over the analysed time period and has reached a plateau in recent years, being 59% in 2013 and 85% in 2020." (PMID 36900294, 2023). "He experienced squamous cell carcinoma transformation, and the EGFR status revealed 19Del plus T790M." (PMID 35888627, 2022). "Another compound, Amlexanox, has been shown to bind S100A4, S100A12 and S100A13 and to reduce proliferation of A431 epidermoid carcinoma cells by inhibiting S100A4 interaction with the Epidermal Growth Factor Receptor (EGFR)." (PMID 36232334, 2022). "In this experiment, we used a total cell protein lysate from two cell lines: EGFR-overexpressing human epidermoid carcinoma cells (A431) and normal cells from mouse embryonic fibroblasts (MEF-WT)." (PMID 36499115, 2022). "The role of EGFR signaling pathway needs to be further explored in the differentiation of squamous carcinoma in the gastric ASC." (PMID 35842595, 2022). "Comparison of EGFR exon 19 deletion and L858R between adenocarcinoma and squamous cell carcinoma in different gender, and between male and female patients in adenocarcinoma or squamous cell carcinoma." (PMID 35061839, 2022). "EGF fusion proteins produced in the cytosol of E. coli have been shown to target human squamous carcinoma-derived A431 cells expressing high levels of EGFR." (PMID 35624572, 2022). "For instance, squamous cell carcinoma patients with EGFR isoform D splicing patterns showed better responses toward EGFR-TKIs." (PMID 36338975, 2022). "Most importantly, upregulation of the long noncoding RNA EGFR-AS1 mediates epidermal growth factor receptor addiction and modulates treatment resistance toward tyrosine kinase inhibitors (TKIs) in squamous cell carcinoma." (PMID 35965679, 2022). "For M0-like and M1-like THP-1 cells, targeted engagement and phagocytosis were observed with the bispecific antibodies after co-incubation with epidermoid carcinoma cells overexpressing EGFR." (PMID 36555321, 2022). "EGFR (Val592Ile), PIK3CA (Arg19Ile), PIK3CA (Arg852Pro), and ROS (Trp847Leu) mutations were present only in the squamous carcinoma population." (PMID 36422072, 2022). "This is consistent with the results in HNSCC,190 which indicates a squamous cell carcinoma feature that EGFR ligand abundance drives the activity of EGFR pathways." (PMID 36198685, 2022). "Literature reports show that the expression of EGFR is generally high in esophageal adenocarcinoma or squamous cell carcinoma." (PMID 36467103, 2022). "Lung puncture biopsy showed squamous carcinoma, and immunohistochemistry showed high PD-L1 expression, TPS ≥ 90%, EGFR mutation (exon 19 deletion) by NGS, and clinical stage IIIC (T3N3M0)." (PMID 35425698, 2022). "All but one patient with stage III squamous cell carcinoma (SCC) were confirmed to have adenocarcinoma and tested for EGFR mutation and ALK rearrangement at diagnosis." (PMID 36434641, 2022). "Next, anti-EGFR blocking antibodies, which inhibited EGFR-induced signaling, showed prominent radiosensitization for squamous cell carcinomas in vitro." (PMID 35409179, 2022). "The lncRNA EGFR-AS1 mediates epidermal growth factor receptor addiction and modulates the drug resistance of squamous cell carcinoma." (PMID 36171196, 2022). "In moderately differentiated squamous cell carcinomas, EGFR immunostaining occurred in 85.7% of cases, moderately or strongly labeling 25–60% of the tumor cells." (PMID 35956111, 2022). "We used the human epidermoid carcinoma cell line A431, which expresses high levels of the EGFR and is a representative cell line for research on EGF-stimulated macropinocytosis." (PMID 35428847, 2022).